DBP (D-box binding PAR bZIP transcription factor)
Diseases named in the same sentence as DBP in open-access papers (continued):
Sharing a sentence is not in itself a finding about the gene and the disease.
Cirrhosis (3 papers, 2016 to 2022). A chronic disorder of the liver in which liver tissue becomes scarred and is partially replaced by regenerative nodules and fibrotic tissue resulting in loss of liver function. "It is key that while DBP haplotype variation is associated with differences in per cent free 25(OH)D, the DBP haplotype effects are far smaller in magnitude than those of pregnancy, cirrhosis, or very old nursing home residents with multiple chronic conditions." (PMID 31191450, 2019). "In this case, the genetic variants DBP-rs4588 and DBP-rs7041 are associated with reduced serum levels of 25-hydroxy-vitamin D [25(OH)D], which may have clinical consequences, which need clarification for cirrhosis and HCC." (PMID 35919232, 2022). "CYP24A1-rs6013897 is associated with cirrhosis and HCC as a predictor, while DBP-rs4588 is associated with reduced vitamin D, and DBP-rs7041 provides increased survival, suggesting a protective characteristic." (PMID 35919232, 2022). "Thus, this study aimed at evaluating the association of genetic polymorphisms of DBP (rs4588 and rs7041) and CYP24A1 (rs6013897) in cirrhosis with or without HCC, considering demographic–clinical–biochemical profile, as well as lifestyle and survival habits." (PMID 35919232, 2022).
epilepsy (3 papers, 2015 to 2021). A brain disorder characterized by episodes of abnormally increased neuronal discharge resulting in transient episodes of sensory or motor neurological dysfunction, or psychic dysfunction. "First, circadian rhythm genes (BMAL1 and CLOCK), and their transcription factor complex, BMAL1–CLOCK, are known to influence the expression of other genes that are causally involved in epilepsy (for example, PAR DBP, TEF, and HLF)." (PMID 33192961, 2020). "Epilepsy causes the upregulation of DBP and MAPK, and while MAPK participates in the progression and promotes the development of epilepsy, DBP activates MAPK through positive feedback." (PMID 25503293, 2015). "Therefore, the expression of DBP and MAPK in epilepsy patients was upregulated, suggesting a possible pathogenetic role in IE." (PMID 25503293, 2015). "The simultaneous co-expression of DBP and MAPK indicated that the interaction of DBP and MAPK may participate in the remodeling of synapses and the drug resistance mechanism of epilepsy." (PMID 25503293, 2015). "However, it is not clear whether DBP, and its interaction with MAPK, participate in mechanisms of drug resistance in epilepsy." (PMID 25503293, 2015).
prostate carcinoma (3 papers, 2010 to 2022). A carcinoma that arises from epithelial cells of the prostate gland. "DBP-maf demonstrated inhibitory activity in proliferation studies of both LNCaP and PC3 prostate cancer cell lines as well as metastatic clones of these cells." (PMID 20976141, 2010). "While DBP-maf (dgVDBP) was demonstrated to inhibit proliferation, migration, and uPAR expression of prostate cancer cells, no inhibitory effect of dgVDBP was estimated due to apoptosis directly." (PMID 35892685, 2022). "Further investigation in prostate cancer cell lines demonstrated that DBP-maf had strong inhibitory activity independent of macrophage activation." (PMID 25428203, 2014).
secondary hyperparathyroidism (3 papers, 2018 to 2025). Overproduction of parathyroid hormone in response to influence external to the parathyroid glands. "Moreover, when placed on a vitamin D deficient diet, the DBP null mice quickly developed secondary hyperparathyroidism and bone mineralization defects such as osteoid thickening that were not seen in DBP sufficient wild-type mice." (PMID 31354633, 2019).
Sepsis (3 papers, 2009 to 2025). Sepsis is defined as life-threatening organ dysfunction caused by a dysregulated host response to infection. "Vitamin D binding protein (DBP) levels were also significantly decreased in critically ill subjects with sepsis which further exacerbates vitamin D insufficiency." (PMID 19389235, 2009). "Furthermore, serum levels of vitamin D binding protein (DBP), the major carrier protein of vitamin D, are decreased in the setting of sepsis leading to lowered levels of 25(OH)D." (PMID 19389235, 2009). "In a study on circadian rhythms in patients with sepsis, it was suggested that sepsis suppresses the expression of the Circadian gene, such as CRY1, REV-ERBα, NR1D2, DBP, and PER2." (PMID 39097582, 2024). "Plasma concentrations of 25-hydroxyvitamin D (25(OH)D), vitamin D binding protein (DBP) and LL-37 in critically ill adult subjects admitted to intensive care units (ICUs) with sepsis and without sepsis were compared to healthy controls." (PMID 19389235, 2009). "We found that vitamin D binding protein (DBP, and also known as Gc-globulin) concentrations were also significantly lower in critically ill subjects with sepsis compared to critically ill subjects without sepsis and healthy control subjects." (PMID 19389235, 2009). "Therefore, we performed a cross-sectional study of vitamin D status including plasma levels of 25(OH)D and vitamin D binding protein (DBP) and their relationship to systemic LL-37 levels in a group of critically ill patients including those with and without sepsis." (PMID 19389235, 2009).
thyroid cancer (3 papers, 2021 to 2023). "The possible stimulation of an intracellular immune-modulating signaling pathway in thyroid cancer oncogenesis in the loss-of-DBP-function in the tumor tissues was suggested." (PMID 36014865, 2022). "We identified a highly polymorphic protein, called vitamin D binding protein (DBP) that could play an important role in thyroid cancer progression in ethnically predisposed group." (PMID 33868582, 2021). "This study concludes that the loss-of-DBP-function in the tumor tissues may stimulate an intracellular immune-modulating signaling pathway in thyroid cancer oncogenesis in Filipino Americans." (PMID 33868582, 2021). "Therefore, we are working on to determine whether a higher frequency of DBP-variants associate to thyroid cancer in Filipino Americans versus European Americans." (PMID 33868582, 2021). "A future study is underway to determine the DBP regulation and its downstream pathways to elucidate strategies to eliminate the observed thyroid cancer health disparities." (PMID 33868582, 2021). "We assayed DBP expression by immunohistochemistry and analyzed the data with confocal microscopy on 200 thyroid cancer archival tissue samples obtained from both ethnicities." (PMID 33868582, 2021). "In the present study, we determined the differential expression of DBP protein in the thyroid cancer tissues and correlated it to cancer staging in Filipino Americans compared to European Americans." (PMID 33868582, 2021). "The interaction of the Enigma and VDR is important as we have found that advanced thyroid cancer has low expression levels of vitamin D binding protein (DBP) in advanced thyroid cancer tissues with a stage-dependent higher expression of the Enigma protein in the corresponding thyroid cancer tissues." (PMID 38132395, 2023). "We also determined whether Knockdown/gain-in-DBP-function in thyroid cancer cell lines further enhanced/decreased cell proliferation and invasion capacities." (PMID 33868582, 2021). "Because of its highly polymorphic nature in humans, a structural/functional defect of DBP gene could contribute to thyroid cancer development and malignant transformation." (PMID 33868582, 2021).
type 1 diabetes mellitus (3 papers, 2020 to 2024). A chronic condition characterized by minimal or absent production of insulin by the pancreas. "Immunostaining of human pancreata reveals generalized loss of DBP expression as a feature of late-onset and long-standing, but not early-onset, type 1 diabetes." (PMID 32553153, 2020).
AIDS (2 papers, 2019 to 2021). A syndrome resulting from the acquired deficiency of cellular immunity caused by the human immunodeficiency virus (HIV). "In this study, we evaluated the association among DBP SNPs and AIDS progression in antiretroviral treatment (ART)-naïve-HIV-infected patients." (PMID 31640710, 2019). "We aimed to study the association among DBP polymorphisms and the patterns of clinical AIDS progression (LTNPs, MPs, and RPs) in ART-naïve HIV-infected patients." (PMID 31640710, 2019). "Since DBP SNPs is associated with VitD levels, it would be plausible that DBP SNPs could be related to AIDS progression." (PMID 31640710, 2019). "DBP rs16846876 and rs12512631 SNPs are related to the patterns of clinical AIDS progression (LTNPs, MPs, and RPs) in ART-naïve HIV-infected patients." (PMID 31640710, 2019). "Regarding HIV infection, there are scarce reports about DBP SNPs and AIDS progression in naïve-HIV-infected patients, whose have found contradictory results." (PMID 31640710, 2019). "DBP rs16846876 and rs12512631 SNPs are related to the patterns of clinical AIDS progression (LTNP, MP, and RP) in ART-naïve HIV-infected patients." (PMID 31640710, 2019). "However, there is scarce information about the influence of DBP SNPs on AIDS progression in naïve-HIV-infected patients." (PMID 31640710, 2019). "Additionally, we found a significant association between DBP haplotypes (composed by rs16846876 and rs12512631) and AIDS progression (LTNPs vs RPs): DBP haplotype AC (aOR = 0.63; q-value = 0.028) and the DBP haplotype TT (aOR = 1.64; q-value = 0.028)." (PMID 31640710, 2019).
alveolitis (2 papers, 2016 to 2019). "In both alveolitis models, DBP null mice had significantly reduced (~50%) neutrophil recruitment to the lungs compared to their wild-type DBP+/+ counterparts, and lung histology showed significantly less inflammation in the null mice." (PMID 31354633, 2019). "The same study also showed that bronchoalveolar lavage (BAL) fluid from wild-type mice had extensive DBP-actin complexes (~75% of total DBP) 4 h after induction of alveolitis." (PMID 31354633, 2019).
colon cancer (2 papers, 2006 to 2021). "There was little effect on E1A level but a reproducible increase in the expression of DBP in all of the colon cancer cell lines infected with the E1A-HD2 virus." (PMID 17020613, 2006).
colorectal cancer (2 papers, 2014). A primary or metastatic malignant neoplasm that affects the colon or rectum. "To further elucidate this association, we examined the molar ratio of 25(OH)D to vitamin D binding protein (DBP), the primary 25(OH)D transport protein, and whether DBP modified the association between 25(OH)D and colorectal cancer risk." (PMID 25036524, 2014).
depression (2 papers, 2024 to 2025). "Several circadian genes were upregulated, including CLOCK, ARNTL, CRY1, DBP, and NR1D1; with associations found between CLOCK and lower state anxiety at baseline, and between CRY2 and higher self-esteem and lower depression at baseline (p < 0.05)." (PMID 41383341, 2025).
endometriosis (2 papers, 2024 to 2025). The growth of functional endometrial tissue in anatomic sites outside the uterine body. "Studies revealed that variants in the VDR gene and DBP serve as genetic risk factors referring to infertility associated with endometriosis and the pathogenesis of endometriosis." (PMID 38698459, 2024). "However, two‐dimensional gel electrophoresis proteomic analysis of serum from women with different stages of endometriosis showed that the disease was associated with threefold higher abundance of DBP relative to controls." (PMID 39739404, 2025). "Despite these discrepancies, genetic studies have suggested that genetic variants in the VDR and DBP genes may play a role in endometriosis-associated infertility." (PMID 38698459, 2024). "In an unbiased analysis of proteins from normal and endometriosis endometrial tissue using two‐dimensional electrophoresis, DBP was identified as one of 16 proteins with increased expression in disease tissue." (PMID 39739404, 2025). "The relatively high circulating levels of the serum vitamin D binding protein (DBP) means that this protein has been measured in a variety of endometriosis settings." (PMID 39739404, 2025). "A further six studies assessed levels of expression or single‐nucleotide polymorphism (SNP) variations for DBP or VDR, and how these variations impact endometriosis." (PMID 39739404, 2025). "Contrary to these findings, the results of two studies have indicated that VDR and DBP gene polymorphisms may have no role in endometriosis susceptibility." (PMID 38698459, 2024). "Although analysis of DBP, VDR, 1α‐hydroxylase and 24‐hydroxylase provides a ‘snapshot’ of the vitamin D system in different endometriosis settings, it is not easy to obtain the tissue required to make these types of measurement." (PMID 39739404, 2025).
food allergies (2 papers, 2024 to 2025). "Polymorphisms affecting vitamin D-binding protein (DBP) can modify the relationship between serum vitamin D levels and food allergy risk." (PMID 40927566, 2025). "Low serum vitamin D concentrations have been associated with food allergies in children, particularly those with certain DBP gene mutations." (PMID 38892458, 2024). "A case–control study found that genetic variations in the DBP gene, particularly rs7041, rs4588, and rs2282679, and vitamin D deficiency may increase the risk of the child of food allergies." (PMID 38892458, 2024). "Another study found that DBP polymorphisms could alter the association between serum vitamin D status and susceptibility to food allergies." (PMID 38892458, 2024).
gestational diabetes (2 papers, 2018 to 2024). Carbohydrate intolerance first diagnosed during pregnancy. "Wang’s study illustrated that Gc rs16847024 and Gc rs3733359 were associated with an increased risk for gestational diabetes, compared to other DBP variants." (PMID 38846489, 2024).
lung carcinoma (2 papers, 2017 to 2024). "Finally, low vitamin D binding protein (DBP) levels were found to be predictive of lung cancer death." (PMID 28301870, 2017). "In contrast, the correlations between PER3, TEF, HLF and DBP are not altered in lung cancer." (PMID 39004631, 2024).
osteoporosis (2 papers, 2016 to 2019). A condition of reduced bone mass, with decreased cortical thickness and a decrease in the number and size of the trabeculae of cancellous bone (but normal chemical composition), resulting in increased fracture incidence. "Some studies have reported DBP variants related to osteoporosis." (PMID 31122237, 2019).
psoriasis (2 papers, 2022 to 2025). An autoimmune condition characterized by red, well-delineated plaques with silvery scales that are usually on the extensor surfaces and scalp. "Given that DBP is a major transporter of all vitamin D forms, and that both DBP and 25(OH)D have been detected in the Very Low Density Lipoprotein (VLDL) molecules, we hypothesized that consequently there would be a deficiency of vitamin D carried by DBP in the HDL molecule in psoriasis." (PMID 39811778, 2025). "High levels of vitamin D-binding protein (DBP) have been reported in patients with psoriasis and the possibility of DBP as a marker of inflammation has been discussed." (PMID 35163226, 2022). "However, the levels of serum-DBP (sDBP) were similar between psoriasis patients and control subjects [sDBP, μg/ml, (IQR): psoriasis 177.80 (125.77–250.99) vs non-psoriasis 177.74 (104.32–254.04), p > 0.99." (PMID 39811778, 2025). "In contrast, using a well-characterized chromatographic method to separate HDL from serum, we firstly confirmed the presence of DBP in the HDL molecule, and surprisingly noted a decrease in DBP contained within the HDL molecule in our psoriasis cohort." (PMID 39811778, 2025).
rickets (2 papers, 2019 to 2020). Bone softening and weakening usually caused by deficiency or impaired metabolism of vitamin D. Deficiency of calcium, magnesium, or phosphorus may also cause rickets. "DBP knock-out mice, in which vitD metabolites are presumably all free and albumin-bound, do not show evidence of vitD deficiency and do not develop rickets." (PMID 32041235, 2020). "In birds, DBP has a much lower affinity for 25OHD2 compared to 25OHD3 and this is supposed to be one of the main reasons for the low biological activity of vitamin D2 for the prevention of rickets in birds." (PMID 31998239, 2019).
schizophrenia (2 papers, 2009 to 2024). A major psychotic disorder characterized by abnormalities in the perception or expression of reality. "Finally, it is important to note that RORB, RORA, and DBP were identified by us recently as possible genes involved in schizophrenia using a pharmacogenomic mouse model and CFG approach." (PMID 19909500, 2009).
systemic lupus erythematosus (2 papers, 2017 to 2024). An autoimmune multi-organ disease typically associated with vasculopathy and autoantibody production. "Serum 25(OH)D (ng/mL), D binding protein (DBP) (ng/mL), free (pg/mL) and bioavailable (ng/mL) vitamin D in Systemic Lupus Erythematosus patients, according to disease activity measured by Systemic Lupus Erythematosus Disease Activity Index (SLEDAI)." (PMID 28085957, 2017).
tuberculosis (2 papers, 2016 to 2019). A chronic, recurrent infection caused by the bacterium Mycobacterium tuberculosis. "The DBP gene has high variability and several single nucleotide polymorphisms (SNPs) in DBP gene have been linked to variations in circulating 25(OH)D concentration, and chronic diseases such as chronic obstructive pulmonary disease (COPD) and tuberculosis." (PMID 31640710, 2019).
AL amyloidosis (1 paper, 2022). AL Amyloidosis is a plasma cell disorder characterized by the aggregation and deposition of insoluble amyloid fibrils derived from misfolding of monoclonal immunoglobulin light chains usually produced by a plasma cell tumor. "In this exploratory study, stored serum samples from 173 patients with newly diagnosed AL amyloidosis were analyzed for vitamin studies which included 25-hydroxyvitamin D [25(OH)D], 1,25-dihydroxyvitamin D [1,25(OH)2D] and vitamin D binding protein (DBP)." (PMID 35800433, 2022).
atherosclerosis (1 paper, 2024). A disease characterized by the build-up of fatty material and calcium deposition in the arterial wall resulting in partial or complete occlusion of the arterial lumen. "Different DBP polymorphisms vary in their ability to activate macrophages, affecting the ability of the human body to control inflammation and prevent atherosclerosis." (PMID 38892458, 2024). "Asp416Glu and Thr420Lys polymorphisms in the DBP gene can influence macrophage behavior and cytokine production, which in turn supports the development of chronic inflammation and atherosclerosis." (PMID 38892458, 2024). "A shift towards the M1 phenotype, which is defined by the generation of pro-inflammatory cytokines that support chronic inflammation and atherosclerosis, is linked to specific DBP polymorphisms." (PMID 38892458, 2024).
autism spectrum disorder (1 paper, 2024). A spectrum of developmental disorders that includes autism, and Asperger syndrome. "In the CHARGE study with 1581 children and their parents, the DBP rs4588 variant was associated with the development of autism spectrum disorder." (PMID 38846489, 2024).
autoimmune disease (1 paper, 2024). A disorder resulting from loss of function or tissue destruction of an organ or multiple organs, arising from humoral or cellular immune responses of the individual to their own tissue constituents. "Furthermore, there was a correlation found between the Lys allele and lower serum levels of 25(OH)D, suggesting a potential association between DBP polymorphisms and vitamin D status in cases of autoimmune disease." (PMID 38892458, 2024).
Autoimmunity (1 paper, 2020). The occurrence of an immune reaction against the organism's own cells or tissues. "Lastly, although a causal role for DBP in α cell dysfunction is suggested by mouse studies, we cannot confidently assert the same in islets of human T1D donors where autoimmunity and species differences come into play." (PMID 32553153, 2020). "Could α cells confer autoimmunity on β cells through paracrine DBP signaling?" (PMID 32553153, 2020).